ULK1 (unc-51 like autophagy activating kinase 1)
Diseases named in the same sentence as ULK1 in open-access papers (continued):
Sharing a sentence is not in itself a finding about the gene and the disease.
breast cancer (continued). "To test whether ULK1 suppresses breast cancer metastasis through phosphorylating Exo70, we analyzed the effect of Exo70 phosphorylation at Ser47, Ser59, and Ser89 on breast cancer metastasis." (PMID 31913283, 2020). "The ULK1-Exo70 interaction was first confirmed by IP assays using tagged proteins exogenously expressed in cells and then with endogenous proteins in different breast cancer cell lines including MDA-MB-231 and MCF-7." (PMID 31913283, 2020). "Furthermore, circCDYL upregulates ATG7 and ULK1 expression by sponging miR-1275, thereby enhancing the autophagy levels and malignant progression of breast cancer." (PMID 33234130, 2020). "It has been shown that GABARAPL1 is a tumor suppressor and this function to be independent of autophagosome formation in hormone responsive breast cancer cells.Moreover, the latest study shows that GABARAPs and LC3s play contrasting roles while regulating ULK1 for autophagy initiation." (PMID 34621117, 2020). "ULK1 expression was lower in the highly metastatic cell lines (MDA-MB-231 and BT-549) than those in the low metastatic cell lines (MCF-7, MDA-MB-453, and Bcap-37), suggesting that ULK1 expression is negatively correlated to the metastatic potentials of human breast cancer cells." (PMID 31913283, 2020). "Here we report that ULK1 suppresses the migration and invasion of human breast cancer cells." (PMID 31913283, 2020). "However, the role of ULK1 and the mechanisms involved in the regulation of breast cancer metastasis are still poorly understood." (PMID 31913283, 2020). "Conversely, in an orthotopic mouse model of breast cancer, the suppression of autophagy via hypoxia-induced expression of the kinase-dead unc-51-like autophagy-activating kinase (ULK1) mutant K46N was found to increase the lung metastasis capacity of MDA-MB-231 cells." (PMID 32615541, 2020). "Elevated expression of ULK1 is known to be inversely correlated with breast cancer metastasis." (PMID 31913283, 2020). "Autophagy is regulated by the ULK1 complex, which plays a key role in autophagosome formation and ULK1 mRNA levels positively correlate with reduced relapse-free survival and therapeutic resistance in breast cancer and nasopharyngeal carcinoma." (PMID 32312983, 2020). "Protective autophagy was induced over a range of treatment doses and was enhanced by an increase in the dose of delphinidin via suppression of the AKT/mTOR/eIF4e/p70s6k signalling pathway and activation of the LKB1/AMPK/ULK1/FOXO3a signalling pathway in HER-2 positive breast cancer cells." (PMID 29587684, 2018). "It has been reported that ULK1 up-regulation may be a mode of breast cancer cell survival and tumor progression." (PMID 30460069, 2017). "Furthermore, circCDYL (hsa_circ_0008285) was reported to augment autophagy of breast cancer cells via regulating the miR-1275-ATG7/ULK1 axis, which may be a potential biomarker for predicting the prognosis of breast cancer patients." (PMID 38177102, 2024). "ULK1 could active autophagy via phosphorylating ATG13 to inhibit the progress of breast cancer." (PMID 37700273, 2023). "Li’s group explored the effect and mechanism of Tan I on breast cancer and found that Tan I could induce autophagy by up-regulating the phosphorylation of AMPKα and its downstream ULK1, thus effectively inhibiting the proliferation of the breast cancer cell line MDA-MB-231." (PMID 36712689, 2022). "Next, AMPK was silenced in breast cancer cells overexpressing CLDN6, and the WB results showed a notable decrease in the expression of p-ULK1." (PMID 40959289, 2025). "Reports have shown that the phosphorylation of ULK1 by MAPK1/3 kinase interacts with BTRC, which leads to subsequent proteasomal degradation and attenuates breast cancer bone metastasis." (PMID 35874839, 2022). "It has been reported that ATG1/ULK1 acts as an upstream signal for actomyosin activation and ATG9A trafficking during the process of autophagy in Drosophila cells and Human breast cancer cells." (PMID 34131310, 2021).
breast cancer (continued). "miR-26a-5p/ULK1 and miR-26a-5p/MAPK6 axis were also regulated by SNHG6 and participated in the development and progression of breast cancer and osteosarcoma, respectively." (PMID 32655318, 2020). "Suppression of autophagy in the hypoxic tumor microenvironment, using hypoxia-induced expression of the dominant-negative mutant of ULK1 or ATG4B, increased fibronectin deposition and facilitated breast cancer cell migration." (PMID 31913283, 2020). "ULK1, a key protein in autophagy, has been suggested the pro-oncogeneic role in human ESCC and breast cancer." (PMID 25714809, 2015). "As a key autophagosomal modulating protein, ULK1 was generally identified as an oncogene and has been detected to be up-regulated in human ESCC and breast cancer." (PMID 25714809, 2015). "Given that the RAF-MAP2K/MEK-MAPK1/3 signaling pathway is frequently activated in breast cancer, particularly in TNBC, the common downregulation of ULK1 in breast cancer supports the rationale for using MAP2K/MEK-MAPK1/3 pathway inhibitors to treat breast cancer bone metastasis." (PMID 39850811, 2024). "Moreover, we reveal that TRPV2 facilitates cancer progression by modulating the CaMKKβ/AMPK/ULK1-autophagic axis through mediating calcium influx, providing new insights into TRPV2 as a novel therapeutic target for breast cancer treatment." (PMID 39334351, 2024). "This study also confirmed that ULK1, as an early regulator of autophagy induction, was directly targeted by ISL-mediated miR-25 that led to autophagic death, improving the chemosensitivity of breast cancer." (PMID 33494431, 2021). "In this study, we demonstrate that ERBB2 promotes autophagy by upregulating ATG12 as well as other autophagy-related (ATG) proteins including ULK1, FIP200, ATG5, and ATG7, leading to breast cancer treatment resistance and worse outcome to patients with ERBB2-positive breast cancer." (PMID 33801244, 2021). "However, the anticancer mechanisms in breast cancer cells and prostate cancer cells mainly occur through activating the AMPK/ULK1 pathway and inhibiting the expression of mTOR/Raptor complex 1 to cause autophagic cell death." (PMID 33494431, 2021). "Importantly, they also found a negative correlation between MAPK1/3 activation and ULK1 expression in primary breast cancer tissues." (PMID 39850811, 2024). "Additionally, in a breast cancer xenograft mouse model, a hypoxia-inducible dominant negative ULK1 to block autophagy in the MDA-MB-231 breast cancer cell line did not have an effect on tumor formation, but increased metastasis to the lungs." (PMID 31554173, 2019).
glioblastoma (29 papers, 2013 to 2026). The most malignant astrocytic tumor (WHO grade IV). "These mutations co-occur with mutations in ULK1 interactors fundamental for the upstream regulation of autophagy, suggesting an impairment of this process in cancer types such as uterine, stomach, skin, glioblastoma and colon cancers." (PMID 32913252, 2020). "BBR-mediated apoptosis blocks the AMPK/mTOR/ULK1 pathway and reduces tumor growth in glioblastoma multiforme (GBM) cells in vivo." (PMID 39309003, 2024). "For example, glioblastoma stem cell-derived, PD-L1-containing exosomes can activate AMPK1/ULK1 signaling cascade-mediated autophagy, thus increasing the resistance of glioblastoma to temozolomide." (PMID 35090497, 2022). "In the KRAS-driven glioblastoma mouse model, autophagy blocked Atg7, Atg13, or Ulk1 by shRNA; inhibited the occurrence and growth of tumors; and extended the survival of mice." (PMID 33194668, 2020). "By focusing on the AMPK/mTOR/ULK1-pathway, berberine stimulates autophagy in glioblastoma." (PMID 36144625, 2022). "The mitochondrial damage caused glioblastoma cells to undergo autophagy preferentially by downregulating the expression of PARL and changing the ratio of BECN1/Bcl‐2 and the process of mitophagy was regulated by the PI3K/Akt/MAPK/mTOR/Ulk1 pathway." (PMID 34799992, 2022). "Additionally, an overexpression of autophagic-related proteins has been observed in a high proportion of glioblastoma patients, with a significant increase of ULK1/ULK2 and TFEB." (PMID 32707662, 2020). "Similarly, deletion of Atg13 or Ulk1 in a KrasG12D-driven glioblastoma decreases tumor progression." (PMID 32308763, 2020). "Interestingly, exosomes derived by temozolomide-resistant glioblastoma (GBM) stem cells containing PD-L1 can induce autophagy with a paracrine mechanism in tumor cells via the AMPK/ULK1 mediated autophagy activation." (PMID 38071322, 2023). "Glioblastoma multiforme (GBM), the most lethal human brain tumor, has lower levels of protein markers of autophagy than low-grade astrocytic tumors; in particular, ULK1 and ULK2 levels are significantly lower in GBM patients than in healthy controls." (PMID 38201453, 2023). "BBR induced glioblastoma cell apoptosis through autophagy activation, which was achieved by the inhibition of the AMPK/mTOR/unc-51-like kinase 1 (ULK1) pathway." (PMID 35269418, 2022). "The present study demonstrates, for the first time, that the treatment of U251 human glioblastoma cells with AA increased MD-mediated AMPK-dependent autophagy through oxidative stress-dependent mTORC1 inhibition and subsequent ULK1 activation." (PMID 35368869, 2022). "Therefore, it could be speculated that increasing autophagy above a certain threshold through excessive ROS generation and subsequent modulation of AMPK/mTOR/ULK1 pathway is responsible for the synergistic cytotoxicity of AA+MD combination in U251 glioblastoma cells." (PMID 35368869, 2022). "There is evidence that hypoxia can also activate mTOR in glioblastoma cell lines; upon activation mTORC1 binds to and phosphorylates ATG13 and ULK1 (as part of the ULK1 complex), upstream of the Beclin/PI3K complex." (PMID 33573362, 2021). "We show that coibamide A induces autophagosome accumulation in human glioblastoma cell types and MEFs via an mTOR-independent mechanism; no change was observed in the phosphorylation state of ULK1 (Ser-757), p70 S6K1 (Thr-389), S6 ribosomal protein (Ser-235/236) and 4EBP-1 (Thr-37/46)." (PMID 23762328, 2013).
colorectal cancer (28 papers, 2016 to 2026). A primary or metastatic malignant neoplasm that affects the colon or rectum. "More recently, it has been shown that DTP in colorectal cancers harbored a diapause-like state dependent on upregulation of the autophagy program and that targeting this pathway with an ULK1 inhibitor drastically reduced tumor recurrences." (PMID 40771583, 2025). "Among these three miRNAs, we found miR-26a-5p was reported to regulate autophagy in colorectal cancer, osteosarcoma, hepatocellular carcinoma, glioma, and laryngeal squamous cell carcinoma by targeting ULK1/2, DAPK1, and ATG12." (PMID 34740994, 2021). "Our study reveals that DSF/Cu regulates autophagy to inhibit proliferation in colorectal cancer through the ULK1 pathway, which provides new evidence for employing this existing drug toward a novel anticancer use." (PMID 34887757, 2021). "The dramatic band shift phenomena were also verified for endogenous ULK1 in human colorectal cancer cells (HCT 116) and human retinal pigmented epithelial cells (RPE1), as well as endogenous ULK1 and exogenous mULK1 in HEK-293T and HeLa cells." (PMID 32516310, 2020). "On the contrary, in colorectal cancer patients, high ULK-1 expression was found to be a predictor of poor prognosis." (PMID 28696368, 2017). "Here we investigated the potential prognostic value of the autophagy-related proteins Beclin-1, p62, LC3 and uncoordinated (UNC) 51-like kinase 1 (ULK1) in a cohort of colorectal cancer (CRC) specimens." (PMID 27444698, 2016). "Fan could induce autophagy by activating the AMPK/mTOR/ULK1 signaling pathway in colorectal cancer cell lines." (PMID 37485535, 2023). "Accumulating evidence indicates that elevated ULK1 expression has been observed in several human cancers, including esophageal squamous cell carcinoma, nasopharyngeal carcinoma, colorectal cancer, gastric cancer, hepatocellular carcinoma, and clear cell renal carcinoma." (PMID 35393404, 2022). "ULK1-mediated autophagy in colorectal cancer could be used as a target for the disulfiram/copper complex (DDC) to inhibit tumor cell growth." (PMID 36505872, 2022). "In colorectal cancer cells, lncRNA SNHG6 targets miR-26a-5p to promote chemotherapy through autophagy induced by ULK1." (PMID 34250091, 2021). "Via binding to TLR4 on colorectal cancer cells, Fusobacterium nucleatum activated the TLR4/MYD88 innate immune signaling pathway and miRNA-18a and miRNA-4802 were downregulated sequentially, which resulted in ULK1 and ATK7 expression." (PMID 30374420, 2018). "This hypothesis is in agreement with other results reported in melanoma and colorectal cancer cells, showing that Vemurafenib treatment was followed by an increase in AMPK activity and high levels of activated ULK1, which in turn, were correlated with autophagy induction." (PMID 34204950, 2021).
gastric cancer (28 papers, 2011 to 2025). A primary or metastatic malignant neoplasm involving the stomach. "The tumor-suppressor roles of Death associated protein kinase 3 (DAPK3) in gastric cancer are associated with increased ULK1 activity and autophagy." (PMID 35393404, 2022). "The inhibition of AMPK and ULK1 decreased DSGOST-induced autophagy in gastric cancer cells, thus leading to an increase in DSGOST-caused cell death." (PMID 29844404, 2018). "Autophagy is increased along with ERK phosphorylation when gastric cancer cells are treated with a proteasome inhibitor, therefore mutations in ULK1 may affect sensitivity to proteasomal inhibitor treatments such as bortezomib as a single agent or in combination with MEK inhibitors." (PMID 21781349, 2011). "Our findings for the first time revealed that PCA inhibited gastric cancer by inducing tumor suppressive autophagy through the AMPK/ULK1 signaling pathway." (PMID 40260299, 2025). "The silence of FTO alleviated the resistance of gastric cancer cells to cisplatin via blocking ULK1-related autophagy." (PMID 40002690, 2025). "In mechanism, PCA-induced autophagy was largely dependent on the AMPK/ULK1 signaling pathway, and blocking the pathway by AMPK specific inhibitor Com C or ULK1 silencing partially reversed the proliferation inhibition of PCA in gastric cancer." (PMID 40260299, 2025). "In this study, we for the first time demonstrated PCA was a specific inhibitor to gastric cancer that triggered tumor suppressive autophagy through the AMPK/ULK1 signaling pathway." (PMID 40260299, 2025). "DAZAP1 upregulation in gastric cancer promotes cell stemness through ULK1-mediated mitophagy and oxidative phosphorylation, revealing a key molecular mechanism in GC progression." (PMID 40401521, 2025). "For instance, a high ULK1 protein expression detectable by immunohistochemistry in gastric carcinomas was found to significantly correlate with a high rate of disease relapse." (PMID 38203816, 2024). "DAPK3 directly phosphorylates Ser556 of ULK1 to increase ULK1 activity and promote the formation of ULK1 complex, leading to inhibition of the proliferation of gastric cancer cells." (PMID 37143582, 2023). "For example, DAPK3 directly phosphorylates Ser556 of ULK1, which increases the activity of ULK1 and promotes the formation of the ULK1 complex, leading to inhibition of the proliferation of gastric cancer cells." (PMID 37143582, 2023). "Knockdown of FTO reversed cisplatin resistance of gastric cancer cells both in vitro and in vivo, which was attributed to the inhibition of ULK1-mediated autophagy." (PMID 36246528, 2022). "Next, we treated with either the presence or the absence of SBI-0206965, which is a small molecule inhibitor for ULK1 in DSGOST-treated gastric cancer cells." (PMID 29844404, 2018). "Remarkably, Ulk1 knockdown by targeted-shRNA inhibited AGS gastric cancer cell survival and proliferation." (PMID 28410240, 2017). "IHC staining assay results further confirmed that 114 gastric cancer tissues showed high Ulk1 expression, and only 31 patients showed low Ulk1 expression." (PMID 28410240, 2017). "The majority (114 out of 145) gastric cancers showed high Ulk1 expression, and the other 31 patients showed low Ulk1 expression." (PMID 28410240, 2017). "The two Ulk1 shRNAs (“1#” and “2#”) both efficiently downregulated Ulk1 in AGS gastric cancer cells." (PMID 28410240, 2017). "We showed that Ulk1 (mRNA and protein) expression was significantly elevated in 12 different fresh human gastric cancer tissues." (PMID 28410240, 2017). "Immunohistochemistry (IHC) staining assay of 145 paraffin-embedded gastric cancer tissues showed that Ulk1 was over-expressed in majority (114 out of 145) of gastric cancer tissues." (PMID 28410240, 2017). "These evidences implied that high Ulk1 expression in human gastric cancer cells should be pro-survival." (PMID 28410240, 2017). "In order to study the function of Ulk1 in gastric cancer cell survival, shRNA strategy was employed." (PMID 28410240, 2017).